DGKA (diacylglycerol kinase alpha)
Diseases named in the same sentence as DGKA in open-access papers (continued):
Sharing a sentence is not in itself a finding about the gene and the disease.
breast carcinoma (12 papers, 2014 to 2022). "Expression of DGKA, whose promoter was hypomethylated among survivors with breast cancer, is associated with worse outcomes across several cancer types, and is known to be important to mammary carcinoma invasiveness." (PMID 35564499, 2022). "With regard to the differential DNA methylation at the DGKA enhancer, it is obvious that H3K27ac in the chromatin pattern requires unmethylated DNA, which was found in the fibroblasts of breast cancer patients with increased fibrosis risk." (PMID 34070078, 2021). "Radiation-induced expression of DGKA regulated by the differentially methylated DGKA enhancer region was previously reported to be associated with higher fibrosis risk in fibroblasts of breast cancer patients who received radiotherapy." (PMID 34070078, 2021). "The proliferation of colon and breast cancer cell lines was markedly suppressed by DGKα-siRNA and R59949." (PMID 34680338, 2021). "Using 3D colon and breast cancer cell cultures, it was demonstrated that DGKα is essential in cell growth and survival by promoting the stabilization of Src activation." (PMID 32722576, 2020). "The growth of colon and breast cancer cell lines was significantly inhibited by DGKα-siRNA and R59949." (PMID 27583247, 2016). "The DGKα/atypical PKC/β1 integrin signaling pathway is essential for matrix invasion of breast carcinoma cells." (PMID 27583247, 2016). "In here we show that upon SDF-1α stimulation of breast cancer cells, DGKα activity mediates aPKCs localization at protrusion sites and the subsequent recruitment of β1 integrin and MMP-9 secretion." (PMID 24887021, 2014). "We previously showed that DGKα is necessary for matrix invasion promoted by Epidermal Growth Factor (EGF) or Hepatocyte Growth Factor (HGF) in MDA-MB-231 breast carcinoma cells." (PMID 24887021, 2014). "Altogether, these data demonstrate that in SDF-1α-stimulated breast carcinoma cells, localized activity of DGKα at pseudopodial tips provides a crucial localization lipid signal for aPKCs recruitment, thus mediating SDF-1α-induced invasive signaling." (PMID 24887021, 2014). "Altogether these data indicate that DGKα, by regulating aPKCs, controls chemokine-induced β1 integrin localization at protrusion sites in breast carcinoma cells, thus confirming the pivotal role of β1 integrin in SDF-1α-promoted matrix invasion." (PMID 24887021, 2014). "Altogether we showed that activation of the DGKα/aPKCs/β1 integrin pathway plays a key role in chemokine-driven matrix invasion in breast cancer cells." (PMID 24887021, 2014). "Using three-dimensional (3D) colon and breast cancer cell cultures, we demonstrate that DGKα upregulation is part of the transcriptional program that results in Src activation in these culture conditions." (PMID 25339152, 2014). "Accordingly, the finding that SDF-1α induces aPKCs localization at protrusion sites through activation of DGKα, indicates that the DGKα/aPKCs signaling axis mediates chemokine-driven mammary carcinoma invasiveness." (PMID 24887021, 2014). "In addition to the effects on apoptosis and proliferation, DGKα is reportedly essential for matrix invasion of breast carcinoma cells through the atypical PKC–β1 integrin signaling pathway." (PMID 34680338, 2021). "In 3D colon and breast cancer models, DGKα was reported to promote cell survival by regulating Src." (PMID 32722576, 2020). "Here, the authors identify a differentially methylated enhancer of the lipid kinase DGKA in fibroblasts from breast cancer patients developing fibrosis after radiotherapy and they show that DGKA inhibition affects lipid homeostasis and reduces pro-fibrotic fibroblast activation." (PMID 26964756, 2016). "To evaluate if our newly synthetised DGKα inhibitors were effective in impairing cancer cell migration, we measured serum induced wound healing in MCF7 breast cancer cells in presence of 10 μM inhibitor." (PMID 31690133, 2020).
breast carcinoma (continued). "In order to investigate the role of DGKα in chemokine invasive signaling in breast cancer, we knocked down DGKα in MDA-MB-231 using a lentiviral construct expressing a DGKα-specific shRNA under an inducible promoter (shRNA-DGKα1)." (PMID 24887021, 2014). "Altogether these data suggest that DGKα and aPKCs may act as signaling nodes in the molecular crosstalk between soluble chemotactic factors and the extracellular matrix, thus prompting us to investigate the involvement of DGKα in cell migration and invasion induced by SDF-1α in breast cancer cells." (PMID 24887021, 2014).
acute myeloid leukemia (6 papers, 2023 to 2026). Acute myeloid leukemia (AML) is a group of neoplasms arising from precursor cells committed to the myeloid cell-line differentiation. "Furthermore, the authors found that high Egr2 and DGKα expression in NK cells infiltrating acute myeloid leukemia and glioma tumors was associated with significantly reduced patient survival compared to NK cells exhibiting low Egr2 and DGKα expression profiles." (PMID 38886578, 2024). "According to cancer expression databases, acute myeloid leukemia (AML) exhibits significant overexpression of multiple DGK isoforms, including DGKA, DGKD and DGKG, without a precise correlation with specific AML subtypes." (PMID 37509516, 2023).
ovarian carcinoma (5 papers, 2014 to 2025). A malignant neoplasm originating from the surface ovarian epithelium. "In particular, they clarified that loss of DGKα selectively ameliorates cisplatin sensitivity in cisplatin‐resistant ovarian cancer in a kinase‐dependent manner via its metabolic product, PA." (PMID 40013327, 2025). "Our previous study demonstrated that DGKA activates the transcription factor cJUN in ovarian cancer cells upon cisplatin treatment." (PMID 36551554, 2022). "So, the JNK-cJUN complex that mediated the transcription of XRCC4 was also possibly promoted by DGKA in the ovarian cancer cells treated with cisplatin." (PMID 36551554, 2022). "In ovarian cancer, it has been shown that DGKα promotes platinum resistance by producing PA, which activates the transcription factor c-JUN and, consequently, enhancing the transcription of cell-cycle checkpoint regulator WEE1 gene." (PMID 36358678, 2022). "This DGKα–c‐JUN–WEE1 signaling pathway reportedly provides cisplatin resistance in ovarian cancer." (PMID 40013327, 2025). "However, at least in human ovarian cancer cell line, it seems that DGKα exhibits specificity for 38:4 (likely, 18:0/20:4) DAG species during invasive migration." (PMID 36358678, 2022). "Since the over-expression of membrane-bound myr-DGKα stimulates cell migration in untransformed cells and pseudopod extension and invasion in A2780 ovarian cancer cells, we investigated whether wild type DGKα over-expression was sufficient to further stimulate invasion in MDA-MB-231 cells." (PMID 24887021, 2014).
endometrial cancer (4 papers, 2014 to 2021). Primary or metastatic malignant neoplasm involving the endometrium (mucous membrane that lines the endometrial cavity). "The inhibition of DGKα by R59949 in KS and endometrial cancer cells leads to decreased cell proliferation, growth, and migration." (PMID 32722576, 2020). "Moreover, upon E2 binding, GPER also regulates in vitro endometrial cancer cells motility and anchorage-independent growth through Diacylglycerol Kinase alpha (DGKα)." (PMID 34831222, 2021). "In line with the potential to regulate migration in endothelial cells by DGKα, a study employing both DGKα specific siRNA and/or DGK pharmacological inhibitor R59949 demonstrated that DGKα activity is a key regulator of migration in Hec-1A endometrial cancer cell line." (PMID 32722576, 2020). "Using the Hec-1A endometrial cancer cell line it has been demonstrated that diacylglycerol kinase alpha (DGKA) activity is required for E2-stimulated cell proliferation, as using DGKA inhibitors resulted in E2-stimulated proliferation and growth of Hec-1A cells." (PMID 32019139, 2020).
lung cancer (4 papers, 2020 to 2025). A malignant neoplasm involving the lung. "In addition, DGKα promotes invasive migration in H1299 lung cancer cells and A2780 ovarian carcinoma cells by controlling Rab coupling protein (RCP)-driven integrin trafficking." (PMID 32722576, 2020). "Interestingly, DGKA had a dual function during cisplatin resistance in two lung cancer cell lines." (PMID 37477536, 2023). "Besides, high levels of DGKα expression correlate positively with lung cancer patient survival, whereas in HCC, the downregulation of DGKα inhibits cell proliferation and metastasis." (PMID 32722576, 2020).
Autoimmunity (3 papers, 2013 to 2025). The occurrence of an immune reaction against the organism's own cells or tissues. "Autoimmune hepatitis is observed in mice that lack both isoforms, suggesting that DGKα and DGKζ have redundant functions in suppressing autoimmunity." (PMID 23531532, 2013). "Apart from concerns with isotype specificity, therapeutic targeting of DGKα and DGKζ could result in deleterious “on-target” effects, such as enhanced cellular proliferation and autoimmunity." (PMID 27800476, 2016). "Neither DGKα- nor DGKζ-deficient mice develop autoimmunity, which may be expected for molecules that suppress T cell activation." (PMID 23531532, 2013). "Mice with conditional gene targeting systems would help clarify the mechanisms of autoimmunity in DGK-deleted mice, as these mice would enable normal T cell development to proceed before gene deletion of DGKα and DGKζ." (PMID 23531532, 2013).
diabetic nephropathy (3 papers, 2017 to 2026). "In diabetic nephropathy, one of diabetes' major complications, a possible therapeutic strategy is the activation of DGKα and DGKδ." (PMID 40859612, 2026). "EGCg activates DGKα to maintain glomerular integrity and podocyte adhesion, mitigating diabetic nephropathy progression." (PMID 41009556, 2025).
viral infection (3 papers, 2016 to 2025). "We previously used DGKα or DGKζ germline knockout (DGKαKO or DGKζKO) mice and demonstrated that a deficiency of either DGKα or DGKζ enhanced effector CD8 T cell expansion after viral infection." (PMID 27014906, 2016). "Collectively, our data highlight the overlap of key significant genes such as DGKA (NK and T-cell viral infection), EGR2 (T-cell viral infection and CD8 T-cell exhaustion), and the potential role of key TFs including EGR2, NFAT2 (NFATc1), and TOX2 in driving NK cell anergy." (PMID 38637625, 2024).
asthma (2 papers, 2019 to 2026). "Plasmids containing the DGKα-encoding gene were inoculated in mice, and asthma was later induced through alum-adsorbed ovalbumin (OVA)." (PMID 31766109, 2019). "Recently, targeting the diacylglycerol metabolism by DGKζ knockdown or treatment with the DGKα-specific inhibitor R59949 has proven to be beneficial for treating asthma by reducing both inflammation and airway hyperresponsiveness." (PMID 31766109, 2019).
autoimmune disease (2 papers, 2019 to 2025). A disorder resulting from loss of function or tissue destruction of an organ or multiple organs, arising from humoral or cellular immune responses of the individual to their own tissue constituents. "Interestingly, DGKα and ζ double deficiency leads to a loss of T cell tolerance and the development of autoimmune diseases in mice (manuscript in preparation)." (PMID 32010133, 2019). "Together, these data suggested that DGKα and ζ intrinsically inhibited Tfr-cell differentiation and that αζDKO Tregs/Tfr-cells and/or exTregs gained dominant functions that could overpower WT Treg/Tfr-cells to cause autoimmune diseases." (PMID 39651265, 2025). "Although DGKα and ζ can function individually to promote T cell anergy and enhance T cell activation in certain experimental settings, neither DGKζ nor DGKα deficiency caused obvious lymphoproliferative or autoimmune diseases." (PMID 39651265, 2025). "The abnormalities in Tregs and the development of multiorgan autoimmune diseases and increased effector CD8+ T-cells in Treg-αζDKO mice but not in DGKα or ζ single knockout mice suggest that DGKα and ζ synergistically prevent Tregs from functional impairment in vivo." (PMID 39651265, 2025).
cervical cancer (2 papers, 2018 to 2020). A primary or metastatic malignant neoplasm involving the cervix. "Moreover, a novel DGKα specific inhibitor CU-3, which was successfully obtained after a high-throughput screening of about 9600 chemical compounds, induced apoptosis in HepG2 HCC cells and HeLa cervical cancer cells, while simultaneously enhancing immune response by promoting IL-2 production." (PMID 32722576, 2020).
diabetes (2 papers, 2017 to 2020). "To investigate whether DGKα is involved in the effects of EGCg on DN, we tested the effects of EGCg on systemic DGKα-deficient mice (DGKα−/−) with STZ-induced diabetes." (PMID 32678222, 2020). "Therefore, we investigated the VtE-induced amelioration of DN in wild-type (DGKα+/+) and DGKα–deficient (DGKα−/−) mice in which diabetes was induced by streptozocin." (PMID 28572624, 2017). "Therefore, this study investigated the involvement of DGKα in the VtE-induced amelioration of DN in DGKα-deficient (DGKα−/−) mice in which diabetes had been induced by streptozocin (STZ)." (PMID 28572624, 2017). "However, the blood glucose concentrations of the DGKα+/+ and DGKα−/− mice with STZ-induced diabetes were not significantly different, because STZ is toxic to pancreatic β-cells." (PMID 28572624, 2017).
hyperglycaemia (2 papers, 2017 to 2025). "Glomerular damage due to hyperglycemia-induced microvascular disorders, polyol pathway activation, cPKC activation, and podocyte loss; DGKα/67LR interactions maintain adhesion." (PMID 41009556, 2025). "Hyperglycemia activates the polyol/cPKC axes and podocyte loss, while DGKα/67LR maintains adhesion." (PMID 41009556, 2025).
primary immunodeficiencies (2 papers, 2021 to 2023). "This paves the way for the use of DGKα inhibitors not only in primary immunodeficiencies but also in other T cell hyporesponsive states such as tumour-induced anergy/exhaustion." (PMID 37138877, 2023). "Thus, the signalling connections and some similarities between those two primary immunodeficiencies prompted us to explore the role of WASp and CDC42 in regulating DGKα activity and DAG-dependent T cell activation." (PMID 37138877, 2023).
renal cell carcinoma (2 papers, 2013 to 2016). "The role of DGKα in anti-tumor responses was studied recently in human tumor-infiltrating CD8+ T cells (CD8-TILs) from patients with renal cell carcinoma (RCC)." (PMID 23531532, 2013). "DGKα has also been evaluated as a potential target to improve T cell activity against tumor, based on the observation that DGKα is upregulated in certain inhibited T cell conditions, such as anergy, and that DGKα is upregulated in tumor-infiltrating lymphocytes in human renal cell carcinoma." (PMID 27800476, 2016).
acute monocytic leukemia (1 paper, 2023). Acute monoblastic leukemia (AML-M5), is one of the most common subtypes of acute myeloid leukemia (AML) that is either comprised of more than 80% of monoblasts (AML-M5a) or 30-80% monoblasts with (pro)monocytic differentiation (AML-M5b). "DGKH consistently showed the lowest expression except in acute monocytic leukemia (AMOL), while DGKZ, DGKD, DGKQ and DGKA exhibited the highest expression levels." (PMID 37509516, 2023).
alcohol dependence (1 paper, 2023). Physical and psychological dependence on alcohol. "Of the DGKα (and 5-HT2A/2C serotonin receptor) inhibitors we analysed, only ritanserin has been tested in human clinicals trials, but in the context of schizophrenia, cocaine and alcohol dependence, and migraines, and it has not been marketed for clinical use." (PMID 36861754, 2023).
ANCA-associated vasculitis (1 paper, 2019). "The finding that stopping PA production by inhibiting DGKα impairs both integrin recycling and secretion suggests that DGKα may represent a viable drug target to reduce tissue injury associated with ANCA-associated vasculitis and other autoimmune disorders where neutrophils play a major role." (PMID 31766109, 2019).
astrocytoma (1 paper, 2023).
bipolar disorder (1 paper, 2018). A disorder of the brain that causes unusual shifts in mood, energy, activity levels and the ability to carry out day-to-day tasks. "Data provided here demonstrate that the previously reported effect of the bipolar disorder treatment lithium on Dictyostelium development is overcome by loss of DGKA." (PMID 30135067, 2018). "We further used Dictyostelium development to analyse a range of compounds associated with both epilepsy and bipolar disorder treatments, to show that loss of DGKA decreases sensitivity to both treatments." (PMID 30135067, 2018). "We further show that loss of DGKA reduces sensitivity to the inhibitory effects of a range of other potential epilepsy treatments and a structurally dissimilar bipolar disorder treatment, lithium." (PMID 30135067, 2018). "The reduction in phosphoinositide signalling caused by VPA, through attenuation of DGKA, might therefore underlie this change in inositol phosphate levels as a potential mechanism for bipolar disorder treatment." (PMID 30135067, 2018). "At a biochemical level, loss of DGKA appears to reduce DAG levels, and exposure to both epilepsy and bipolar disorder treatments increases DAG levels." (PMID 30135067, 2018). "Thus, these experiments suggest that, in Dictyostelium, loss of DGKA attenuates a common cellular effect of VPA relating to both epilepsy and bipolar disorder treatments, and that a range of new compounds with this effect should be investigated as alternative therapeutic agents." (PMID 30135067, 2018). "In this study, we employed the simple biomedical model system Dictyostelium to investigate the cellular mechanisms of the epilepsy and bipolar disorder treatment, VPA, through the key enzyme, DGKA, which is responsible for the phosphorylation of DAG to PA." (PMID 30135067, 2018). "In our current study, we show that novel compounds (decanoic acid and 4-ethyloctanoic acid) function through modulating a DGKA-related pathway commonly affected by lithium and VPA, suggesting that these compounds should be investigated as new treatments for bipolar disorder as well as epilepsy." (PMID 30135067, 2018).
brain cancer (1 paper, 2022). A primary or metastatic malignant neoplasm affecting the brain. "No existing inhibitor is known to meet all these criteria, but the strong potential of DGKα inhibition against this lethal brain cancer should help drive development and testing of agents to bring this promising strategy to the clinic for patients with GBM." (PMID 35267577, 2022).
brain tumor (1 paper, 2022). "While we have focused here on GBM, there is every indication that DGKα inhibition will be applicable to other brain tumor types as well." (PMID 35267577, 2022).
breast tumor (1 paper, 2014). "Higher DGKα protein levels were also observed for breast tumor-derived cell lines in 3D cultures suggesting a direct correlation with 3D imposed restrains." (PMID 25339152, 2014).
cholangiocarcinoma (1 paper, 2024). A carcinoma that arises from the intrahepatic biliary tree (intrahepatic cholangiocarcinoma) or from the junction, or adjacent to the junction, of the right and left hepatic ducts (hilar cholangiocarcinoma). "This is the first report to investigate the relationship between the pathological DGKα expression level and the clinicopathological features in cholangiocarcinoma." (PMID 38716625, 2024).